LINC02223 (long independently transcribed non-coding RNA 2223)
Gene: Long non-coding RNA gene on chromosome 5 (17,684,584 to 17,955,857, forward strand). Ensembl gene ENSG00000249937.
Diseases named in the same sentence as LINC02223 in open-access papers:
LINC02223 is named in the same sentence as 1 disease in open-access papers, as found by Europe PMC text mining. Sharing a sentence is not in itself a finding about the gene and the disease.
LINC02223 shares sentences with these, for which no sentence is quoted: depression (1 paper).